EIF1AX (eukaryotic translation initiation factor 1A X-linked)
Diseases named in the same sentence as EIF1AX in open-access papers (continued):
Sharing a sentence is not in itself a finding about the gene and the disease.
cancer (continued). "While the contribution of EIF1AX to tumorigenesis and cancer progression is not clear, EIF1AX has been found to have links to cancer-related signaling pathways including PI3K/AKT/mTOR and Ras/ERK signaling pathways, as well as oncogene c-myc." (PMID 36589683, 2022). "The TERT and EIF1AX gene locations were not included in the applied cancer panel." (PMID 29133385, 2018).
EIF1AX also shares sentences with these, for which no sentence is quoted: blue nevus (1 paper); breast tumours (1); ciliary body melanomas (1); conjunctival melanomas (1); gastric cancer (1); glioblastoma (1); glioma (1); lung adenocarcinoma (1); lung carcinoids (1); lymph node metastasis (1); melanocytic neoplasm (1); metabolic syndrome (1); multinodular goiter (1); poorly differentiated thyroid cancers (1); renal cell carcinoma (1); Thyroid adenoma (1).